APOBEC3B (apolipoprotein B mRNA editing enzyme catalytic subunit 3B)
Diseases named in the same sentence as APOBEC3B in open-access papers (continued):
Sharing a sentence is not in itself a finding about the gene and the disease.
tumor (continued). "Irrespective of ESR1-status, we showed that APOBEC3B expression was increased in distant metastases compared to the corresponding primary tumor, with highest expression in liver, lung, brain and bone metastases." (PMID 28141868, 2017). "Furthermore, since the pattern of APOBEC3B expression in primary tumors is retained and even increased in paired metastases, and shows a trend toward a possible metastatic location-specific pattern, one could envision that the primary tumor is already ‘primed’ for an eventual site of dissemination." (PMID 28141868, 2017). "Another note is that the assay we used to determine APOBEC3B copy numbers does not discriminate between germline and tumor-specific (i. e. somatic) APOBEC3B deletion." (PMID 27552096, 2016). "Indeed the expression levels of APOBEC1, APOBEC3B, APOBEC3C and APOBEC3F were found to be significantly higher in both primary and metastatic tumours as compared with normal tissues (P<0.01)." (PMID 26647728, 2015). "The tumor/normal (T/N) ratio of APOBEC3B/β-actin mRNA levels was not different within the gender, age, smoking status and pathological stages." (PMID 24748981, 2014). "In our analyses, APOBEC3B was highly expressed and common in NSCLC tumor cells." (PMID 24748981, 2014). "Tumor/normal (T/N) ratio of the APOBEC3B/β-actin mRNA level did not correlate with gender (male vs. female, P=0.4694), ages (age ≤65 vs. >65, P=0.9050) and smoking status (smoker vs. non-smoker, P=0.1151)." (PMID 24748981, 2014). "In contrast, high expressing, but not low expressing APOBEC3B-exposed cells decreased tumor size." (PMID 41675410, 2026). "In the tumour samples, the majority of epithelial (tumour) cells expressed neither APOBEC3A nor APOBEC3B at levels detectable by scRNA-seq, and the only datasets containing a significant number of cells expressing APOBEC3A and/or APOBEC3B were from HNSCC or ESCC." (PMID 39548236, 2025). "APOBEC3B expression does not increase tumor growth rate or the number of tumors per animal." (PMID 38254863, 2024). "Inducing APOBEC3A and APOBEC3B for tumor levels may not accurately mimic the carcinogenesis arising in pre-malignant tissues given their generally lower expression in normal tissues." (PMID 38254863, 2024). "Moreover, we observed a statistically significant positive correlation between the immune infiltration of CD8+ T-cells and the expression level of APOBEC3B in HNSC0-HPV+ and UVM tumors based on most algorithms, while the ESCA tumor type was negatively correlated." (PMID 35918642, 2022). "Patients who do not carry the germline deletion and have either a tumor-specific homozygous deletion or a heterozygous deletion of APOBEC3B in combination with a high tumor cell percentage may also be misclassified." (PMID 27552096, 2016). "In our study, the tumor in which APOBEC3B gene locus was deleted did not express APOBEC3B mRNA." (PMID 27977754, 2016). "Furthermore, it has been proposed that hypermutation in the absence of APOBEC3B generates tumour-specific antigens which activate the immune system." (PMID 27233495, 2016). "Homozygous deletion of APOBEC3B did not affect the tumor aggressiveness or the prognosis." (PMID 27977754, 2016). "APOBEC3B does not fit into classical tumor suppressor/oncogene paradigms." (PMID 25848704, 2015). "Thus, the deletion of APOBEC3B gene locus might be a mechanism of lacking APOBEC3B mRNA in this tumor." (PMID 27977754, 2016). "However, APOBEC3B expression did not correlate with metastasis or tumor invasion." (PMID 24748981, 2014). "Tumor samples in this cohort with normal FHIT expression do not exhibit APOBEC hypermutation, despite having high APOBEC3B expression." (PMID 25401976, 2015).
infection (13 papers, 2018 to 2025). The state of being infected such as from the introduction of a foreign agent such as serum, vaccine, antigenic substance or organism. "APOBEC3B relocalization occurs rapidly following infection suggesting the involvement of an immediate early or early (IE/E) viral protein." (PMID 37565748, 2023). "Among the APOBEC protein family members, APOBEC3A and APOBEC3B are able to restrict the infection of multiple viruses, including parvovirus, hepatitis B virus (HBV), human papillomavirus, human immunodeficiency virus 1 (HIV-1) and carcinogenesis." (PMID 37903974, 2023). "BKPyV-infection significantly increased deaminase-activity against a linear probe with an RTCA motif that is the substrate preference of APOBEC3B (mean log2 fold change 1.66 ± 1.05; p = 0.0303)." (PMID 35194151, 2022). "Additionally, nuclear BORF2-APOBEC3B bodies that formed in early lytic infection contained SUMO, suggesting the importance of SUMOylation in the sequestration of APOBEC3B." (PMID 40838749, 2025). "In addition, connections between APOBEC3B upregulation by infection with human papillomavirus/BK polyomavirus and tumorigenesis have been reported." (PMID 39769470, 2024). "In this study, we find that APOBEC3B forms a complex with PABPC1 to stimulate PKR and counterbalances the PKR-suppressing activity of ADAR1 in response to infection by many types of viruses." (PMID 36781883, 2023). "BKPyV-infection led to significantly elevated APOBEC3A and APOBEC3B protein, increased deaminase activity and greater numbers of apurinic/apyrimidinic sites in the host urothelial genome." (PMID 35194151, 2022). "However, a deleted APOBEC3B locus together with inactive APOBEC3H haplotypes (i.e., hapIV, which likely has no anti-viral activity at all) may increase the susceptibility to infection by HTLV-1 with severe implications for disease progression." (PMID 32013205, 2020). "No significant change was observed with the expression of ADAR1–3, APOBEC1, APOBEC2, and APOBEC3A 3D, 3G, and 3H, whereas APOBEC3B, and 3C had a significant decrease, and APOBEC3F had a significant increase in A549 cells during the course of infection with H7N9." (PMID 29363430, 2018).
adenocarcinoma (3 papers, 2014 to 2015). A common cancer characterized by the presence of malignant glandular cells. "The T/N ratio of the APOBEC3B/β-actin mRNA level did not correlate with pathological stages and subtypes (adenocarcinoma vs. others, P=0.5031)." (PMID 24748981, 2014).
APOBEC3B also shares sentences with these, for which no sentence is quoted: diffuse large B-cell lymphoma (4 papers); acute myeloid leukemia (3); lung squamous cell carcinoma (3); lymphoid neoplasm (3); malaria (3); multiple myeloma (3); Breast (2); glioblastoma multiforme (2); human papilloma virus infection (2); ovarian tumor (2); pancreatic ductal adenocarcinoma (2); prostate adenocarcinoma (2); triple-negative breast carcinoma (2); astrocytoma (1); autoimmune disease (1); benign tumors (1); brain tumors (1); brainstem glioma (1); cardiomyopathy (1); cervical adenocarcinoma (1); cervical tumors (1); chondrosarcoma (1); chronic lymphocytic leukemia (1); chronic myelogenous leukemia (1); colon adenocarcinoma (1); Ductal Carcinoma (1); endometriosis (1); gallbladder cancer (1); heart failure (1); leukemia (1).
A further 22 diseases each share a sentence with APOBEC3B in 1 paper.